IL1B (interleukin 1 beta)
Diseases named in the same sentence as IL1B in open-access papers (continued):
Sharing a sentence is not in itself a finding about the gene and the disease.
lupus (116 papers, 2008 to 2025). "In this study, we examined how loss of IL-1β modulates disease in the NZM2328 lupus-prone mouse model." (PMID 37261358, 2023). "Previously, IL-1β has been shown to be released associated with exosomes from dendritic cells in patients with lupus." (PMID 32993051, 2020). "Meanwhile, it was reported that NLRP1/IL-1β polymorphism was correlated with the pathogenesis of autoimmune diseases including lupus; however, exact evidence about how NLRP1 was involved in lupus was not illustrated." (PMID 31427885, 2019). "In several inflammatory diseases, including lupus and Crohn's disease (CD), elevated IL-1β production is associated with IL-1Ra." (PMID 30946009, 2019). "The fact that it is difficult to induce lupus in IL-1b-deficient mice indirectly suggests that IL-1b has an irreplaceable role in the pathogenesis of SLE." (PMID 30202244, 2018). "This was associated with a dramatic decrease in kidney IL-4 and IL-1β pro-inflammatory cytokines concentrations as we previously demonstrated in the Lyn−/− lupus-like model." (PMID 28801578, 2017). "We reported here that deliberate inhibition of selected DLK1-Dio3 miRNAs such as miR-154, miR-379, and miR-300 significantly reduced the production of lupus-associated cytokines IFNγ, IL-1β, IL-6, and/or IL-10." (PMID 27070142, 2016). "In contrast with the concept of a critical role for inflammasome activation in autoimmunity, inflammasome deficiency due to a point mutation in the NLRP3 gene has recently been identified in lupus-prone NZB/W F1 mice correlating with reduced IL-1β release." (PMID 26579125, 2015). "Here, we examine how loss of IL-1β affects disease severity in the lupus-prone NZM2328 mouse model." (PMID 37261358, 2023). "In pristane-induced lupus, Lactobacillus strains reduce Th17 frequency by inhibiting IL-1β/NLRP3 inflammasome signaling and upregulating TGF-β/Smad3 to expand Tregs." (PMID 40534849, 2025). "Probiotics like L. rhamnosus LC-STH-13 inhibit NF-κB activation by blocking TLR9 signaling and preventing IκBα degradation, thus reducing pro-inflammatory cytokines such as TNF-α, IL-6, and IL-1β in lupus-prone mice." (PMID 40534849, 2025). "Activation of spinal microglial GPR109A suppresses p38 MAPK signaling and diminishes glutamatergic synaptic activity by decreasing IL-18 and IL-1β production in the dorsal horn of female lupus mice with chronic pain." (PMID 41511304, 2025). "Fli-1′s regulation of the IL-1β and IL-18 genes in lupus mice was further confirmed in the lung pericytes of Cecal ligation and puncture (CLP)-induced sepsis models." (PMID 40305194, 2025). "In lupus mice with chronic pain, IL-1β in the spinal dorsal horn enhances glutamatergic synaptic activity by suppressing glial glutamate transporter activity." (PMID 38612414, 2024). "In lupus-prone mice, I3A/IL-1β-MSCs decreased the serum levels of anti-dsDNA and total IgG antibodies more than I3A-MSCs did." (PMID 39684336, 2024). "Studies have suggested that there may be a dysregulation of inflammasome activation in lupus, and they have also shown that IL-1β is produced in greater amounts in the kidneys of human monocytes and mice at risk of the disease, respectively, while IL1b gene expression is elevated." (PMID 38666950, 2024). "This study suggests that enhanced CSF-1 signaling activity in the spinal dorsal horn leads to thermal hypersensitivity in lupus mice by releasing IL-1β from microglia and suppressing glial glutamate transporter activity." (PMID 38612414, 2024). "Activation of the microglial GPR109A receptor in the spinal dorsal horn attenuates glutamatergic synaptic activity and hypersensitivity in lupus mice by suppressing the overproduction of spinal IL-1β and IL-18." (PMID 38612414, 2024). "The activation of spinal GPR109A with MK1903 resulted in the attenuation of p38 MAPK activity and glutamatergic synaptic activity by suppressing the production of IL-18 and IL-1β in the spinal dorsal horn of lupus mice with chronic pain." (PMID 38612414, 2024).
lupus (continued). "This enhanced glutamatergic synaptic activity and the resulting chronic pain in lupus mice are attributed to the overproduction of proinflammatory cytokines (such as IL-1β and IL-18), CSF-1, and thrombin, as well as reduced AMPK activity in the same region." (PMID 38612414, 2024). "It has been reported that the activation of glial cells in the spinal dorsal horn of lupus mice experiencing chronic pain was accompanied by the increased production of IL-1β, IL-18, and cathepsin B." (PMID 38612414, 2024). "The activation of microglial GPR109A receptors in the spinal cord mitigates thermal hyperalgesia in female lupus mice by suppressing the production of IL-1β and IL-18, as well as p38 MAPK (see Section 6.5 for details)." (PMID 38612414, 2024). "CD39 is upregulated in systemic lupus erythematosus (SLE) patients who exhibit increased levels of ATP that binds to P2X receptors resulting in activation of the inflammasome, release of IL-1β, and other cytokines associated with disease pathogenesis." (PMID 37705981, 2023). "Increased levels of miR-146a are related to the inhibition of pro-inflammatory cytokine production (IL-6, TNF-α, and IL-1β) and the expression of inflammatory mediators, leading to the survival of lupus-prone mice." (PMID 37372034, 2023). "In this study, we uncovered a novel sex-biased protective role for IL-1β in limiting renal pathology in the lupus-prone NZM2328 mouse model." (PMID 37261358, 2023). "Consistent with these previous findings, we found that levels of phosphorylated ERK and TNFα and IL-1β protein in lupus mice were higher than those in normal controls." (PMID 37440542, 2023). "Pristane-induced lupus mice showed significantly higher serum levels of IL-1β, IL-2, IL-4, IL-13, IL-21, and IL-22 compared to those in WT mice." (PMID 35911685, 2022). "Our findings showed that IL-1β expression was higher in pristane-induced lupus mice, and expression of IL-1β was significantly inhibited by GDF-15 treatment." (PMID 35911685, 2022). "GDF-15 treatment significantly reduced levels of IL-1β, IL-2, IL-4, IL-21, and IL-22, by which treatment of lupus mice with 100 μg/kg GDF-15 had the most efficiency." (PMID 35911685, 2022). "Unsurprisingly, our results revealed that IL-6 and IL-1β cytokine levels in the hippocampus of lupus mice were significantly higher than those in the control mice, with albumin accumulation in situ (data not shown)." (PMID 34645459, 2021). "Baicalein also inhibited NLRP3 inflammasome activation by decreasing the expression of NLRP3, caspase-1, and IL-1β, the activation of NF-κB by suppressing NF-κB phosphorylation, and the levels of ROS in pristine-induced lupus mice and LPS-stimulated MDSCs." (PMID 33418975, 2021). "Further, in addition to IFNα, pristane induces production of numerous NFκB-induced cytokines, including IL-6, IL-1b, and TNFα, which contribute to other manifestations of lupus." (PMID 33101313, 2020). "Normalizing ERK1/2 in lupus‐prone mice reduced expression of IL‐1β, TNF‐α and IL‐6 and relieved development of lupus." (PMID 33079487, 2020). "The results showed that plasma levels of TNF‐α, IL‐1β, IL‐6 and IL‐23 were significantly up‐regulated in pristane‐induced lupus mice compared with those in the control group." (PMID 33079487, 2020). "The results showed that the serum levels of IL-1β and IL-18 remarkably increased in lupus mice, while baicalein significantly inhibited the production of these cytokines." (PMID 31023362, 2019). "Western blot analysis showed that baicalein decreased mature caspase-1 p20 subunit and IL-1β in kidneys of lupus mice." (PMID 31023362, 2019). "In a model of lupus nephritis, the HDAC inhibitor ITF2357 diminished the proinflammatory gene expression of il6, il-1β, and the systemic lupus erythematosus (SLE) serum biomarker IgG2a." (PMID 30647531, 2018). "IL-1β and IL-18 are two members that have been shown to play a role in murine lupus-like models, but their role in human SLE remains poorly understood." (PMID 29930551, 2018).
lupus (continued). "Abnormal production of inflammatory cytokines such as IFNγ, IL-1β, IL-6, and TNFα is a key characteristic of lupus." (PMID 27070142, 2016). "Although IL-1β is predominantly secreted by infiltrating macrophages, it is also locally synthesized in the kidney of lupus-prone mice and its level correlates with the severity of nephritis." (PMID 26441980, 2015). "An increase in expression of the pro-inflammatory cytokine IL-1β has been noted in the cutaneous lesion and Peripheral Blood Mononuclear Cells (PBMCs) from lupus patients." (PMID 25324778, 2014). "Therefore, enhanced TLR7 signaling in lupus mice likely amplifies neuronal activity and promotes spinal central sensitization by increasing the production and release of IL-1β and IL-18." (PMID 41511304, 2025). "Moreover, administering GDF-15 to lupus-prone mice led to a decrease in several proinflammatory cytokines, including IL-1β, IL-18, and IL-22, highlighting its role in modulating the immune response." (PMID 40722837, 2025). "Notably, the selective GSK3β inhibitor TDZD-8 effectively blocked NLRP3/IL-1β activation in peripheral blood mononuclear cells from patients with systemic lupus erythematosus." (PMID 40526103, 2025). "This indicates that IL-1β-stimulated increases in HexCers is due largely to increases in GlcCer (rather than GalCer) and supports our previous observations that elevated HexCers in the kidneys of lupus-prone mice are due to increased GlcCers." (PMID 41451198, 2025). "In addition, CB exhibits broader-spectrum activity in purified pDCs and in a lupus mouse model, significantly reducing levels of pro-inflammatory cytokines IL-1β, IL-17, TNF-α and the interferon-regulated gene TRAIL, both in vitro and in vivo." (PMID 39737176, 2024). "Notably, experimental studies utilizing lupus models have provided compelling evidence supporting the link between increased expression of IL-1β and the severity and accelerated progression of the disease." (PMID 38745067, 2024). "The involvement of IL-1β and IL-18 in the development of chronic pain induced by SLE was evident in experiments where spinal topical applications of IL-1β or IL-18 antagonists prolonged the latency of hind paw withdrawal responses to radiant heat stimuli in lupus mice." (PMID 38612414, 2024). "It was reported that the protein expression of pro-inflammatory cytokines like TNFα and IL-1β, and ERK activity, were increased in the DRG in lupus mice with chronic pain, which were also associated with increased excitability in nociceptive sensory neurons in the DRG." (PMID 38612414, 2024). "Additionally, the levels of supernatant IL‐1α and IL‐1β, specific products of Caspase 11 activation, were also increased following incubation with lupus serum." (PMID 38881675, 2024). "This may also be evidence that increased levels of IL-1β in lupus is an extraneous consequence of inflammasome activation and not actually indicative of a pathogenic effect." (PMID 37261358, 2023). "AA genotype carriers of rs3806268 may directly increase IL-1β production in systemic lupus erythematosus disease." (PMID 36051474, 2022). "Of note, IL-1β promotes significant improvement in the functional capacity of lupus EPC/CAC." (PMID 36420265, 2022). "Importantly, the inhibition of HA in lupus-prone mice improved disease parameters, at least partially by reducing the expression of pro-inflammatory cytokines, including IL-1β, TNFα, and IL-6, in the kidney." (PMID 33240280, 2020). "In addition to delaying lupus disease manifestations, fish oil reduced the expression of IL-1β, TNF-α, and ICAM-1 in (NZB x NZW)F1 (BW) mice, while it increased the expression of antioxidant enzymes." (PMID 31137916, 2019). "We have previously demonstrated that IL-1β overexpression in lupus-prone mice is detectable at an early stage of disease, and it has been shown that activation of the TNF-RI-signaling pathway is sufficient to induce upregulation of adhesion molecules and homeostatic chemokines, and TLS formation." (PMID 29777158, 2018).
lupus (continued). "Systemic lupus erythematosus and other autoantibody-mediated AID show a pathogenic role for T1-IFNs, while T-cell-mediated AID, such as MS, are driven primarily by GM-CSF-stimulated IL-1β production." (PMID 28424682, 2017). "Finally, inhibition of select DLK1-Dio3 miRNA such as miR-154, miR-379 and miR-300 with specific antagomirs significantly reduced the production of lupus-relevant IFNγ, IL-1β, IL-6, and IL-10 in lipopolysaccharide (LPS) activated splenocytes from MRL-lpr mice." (PMID 27070142, 2016). "IL-1β promotes a Th17 cell response, which is increased in lupus." (PMID 25324778, 2014). "Together, common characteristics of lupus appear to be upregulation of members of the IL-1 family such as IL-1α and IL-1β and IL1R2, of the TNF/death receptor family such as TNF receptor II (TNFRSF1B), TRAIL (TNFSF10), and its decoy receptors, and a gene signature of IFN-α/β-regulated genes." (PMID 19884985, 2009). "Given that IL-1β can trigger a broad range of responses that drive systemic inflammation and exacerbate damage during chronic disease, we hypothesized that inhibition of this cytokine would limit disease severity in a lupus-prone mouse model." (PMID 37261358, 2023). "Finally, severe complications occurring in lupus patients, such as macrophage activation syndrome or pericarditis, have been successfully reduced with anakinra, an IL-1b antagonist, showing that both IFNs-I and IL-1 participate in lupus pathogenesis, at least in a subset of patients." (PMID 34066649, 2021). "We found that IL-1β induction by Fcgr2b−/− BMDMs stimulated with IgG IC was restored to WT levels by the addition of 2DG, suggesting that it may potentially ameliorate macrophage-induced inflammation in lupus." (PMID 32541026, 2020). "In addition, IL-1β−/− and IL-1α/β−/− mice are resistant to the induction of experimental lupus." (PMID 27250627, 2016). "Correlation between serum IL-1β level and disease activity in SLE patients further highlights the importance of IL-1β in the pathogenesis of lupus nephritis." (PMID 26441980, 2015). "The three Lactobacillus strains improved hepatic injuries and reduced inflammation in lupus-prone mice by suppressing MAPK/NF-κB signaling pathways and lowering IL-1β, IL-6, and TNF-α expression." (PMID 40534849, 2025). "Other emerging agents, including IL-6,IL-1β, and BTK inhibitors, aim to reduce inflammation-driven CVD, echoingfindings from non-lupus trials like CANTOS." (PMID 41356287, 2025). "Consistent with previous findings, the abundance of phosphorylated ERK, IL-1β, and TNFα proteins in the DRG of lupus mice was notably higher compared to normal controls." (PMID 38612414, 2024). "Some studies have identified increased expression of IL-1β in the serum of SLE patients and in lupus-prone mouse models." (PMID 37261358, 2023). "Besides, in patients with active SLE and a mouse model of lupus, the enhanced MDSCs induced Th17 cells differentiation in an arginine-dependent manner and altered the ratio of Th17 cells and Treg cells via ROS and IL-1β dependent manner, thereby exacerbating disease progression." (PMID 36569895, 2022). "John’s wort) proved effective in significantly reducing the serum level of IFN-g, IL-17A, IL-1b, TNF-a, and IL-6 in lupus-prone mice." (PMID 35431950, 2022). "In our present study, based on mice models, we found that GDF-15 alleviated lupus by reducing renal damage, reversing CD8+, CD19+, and TH2 cells dysregulation, inhibiting production of IL-1β, IL-2, IL-4, IL-21, IL-22, ANA, and total IgG." (PMID 35911685, 2022). "Percentages of CD8+, CD11b+, CD19+, CD11C+ cells, TH2 cells, and pro-inflammatory cytokines (IL-1β, IL-2, IL-4, IL-21, and IL-22) were reduced after GDF-15 treatment in lupus mice." (PMID 35911685, 2022). "EGCG also inhibited NLRP3 inflammasome activation by reducing NLRP3 expression and production of active caspase-1, IL-1β, and IL-18 in NZB/W F1 lupus-prone mice." (PMID 33418975, 2021).
lupus (continued). "For instance, resveratrol ameliorated the disease symptoms by reducing B and Th1 cells in lupus-prone mice, decreasing inflammatory cytokines (TNF-α and IL-1β) in RA-induced rats and inhibiting cell adhesion molecules (ICAM and VCAM) in db/db mice." (PMID 33333788, 2020). "We demonstrated that Arg-1 and IL-1β secreted by MDSC drive TH17 cell differentiation in mouse models and patients with systemic lupus erythematosus (SLE) and arthritis." (PMID 32391010, 2020). "Upon repeated injection of apoptotic cells, these mice developed a systemic lupus erythematosus (SLE)-like disease, with increased levels of pro-inflammatory cytokines, such as IL-6, IL-1β, IL-12, autoantibodies, and a decreased level of the anti-inflammatory cytokine, IL-10." (PMID 31665027, 2019). "Activation of miR-654 reduced IL-1β, IL-6, IL-8, and TNF-α production, reduced gomerulonephritis, and decreased MIF, IgG, and C3 expression in murine lupus glomeruli." (PMID 31608058, 2019). "The phenolic fraction of extra virgin olive oil has anti-inflammatory and immunomodulatory properties that associated with a reduced production of pro-inflammatory TNF-α, IL-6, IL-1β, and IFN-γ in 38 lupus patients’ peripheral blood mononuclear cells (PBMCs)." (PMID 31137916, 2019). "It was found that TNF-α, IL-1β, IL-6, IL-12 and MCP-1, which were upregulated in kidneys of ALD-DNA-induced lupus mice, were decreased in the pSAP-treated lupus mice." (PMID 21799927, 2011). "Analysis of the cytokine profile in serum of mice further confirmed that the inflammatory markers (including TNF-α, IL-1β, IL-6, IL-12, and MCP-1) were extensively and dramatically decreased in pSAP-treated lupus mice as compared with other control groups." (PMID 21799927, 2011). "Changes of this magnitude are biologically significant, because lupus patients have elevated serum TNF-α and IL-1β concentrations of a similar magnitude compared with controls." (PMID 20049214, 2009). "Furthermore, GSK3β contributes to lupus nephritis development in lupus-prone mice, in part through activation of the NLRP3/IL-1β axis." (PMID 40526103, 2025). "The P2X7 receptor is involved in systemic lupus erythematosus through the activation of the NLRP3 inflammasome and increased production of IL-1β and IL-18 by lupus patient-derived macrophages, thereby contributing to the cardiovascular, cutaneous, and renal manifestations of lupus." (PMID 41002432, 2025). "Naja naja atra snake venom and its toxin neurotoxin-Nna has been shown to decrease IL-1β and TNF-α levels in the kidney and the serum of rats, respectively; in addition, N. n. atra venom can inhibit IL-6 and TNF-α production in systemic lupus erythematosus in mice." (PMID 36828473, 2023). "Importantly, expression of pro-inflammatory cytokines (IL-1β, IL-6, TNFα and IFNγ) was increased in PVAT from lupus mice, concomitant with elevated plasma levels of TNFα, IFNγ and IL-6." (PMID 37006244, 2023). "Moreover, studies with azithromycin and monocytes from systemic lupus erythematosus patients revealed that the PI3K signalling pathway is involved in the regulation of cytokine secretion (IL-6, IL-1β, IL-10)." (PMID 35742807, 2022). "One study showed that EGCG was able to prevent the development of LN in NZB/WF1 lupus-prone mice due to inactivation of the Nrf2 antioxidant pathway, which resulted in renal NLRP3 inflammasome inactivation with less amounts of IL-1β and IL-18 in kidney lysates." (PMID 34830358, 2021). "Exosomes derived from lymphocytic leukemia (CLL) can target TLR7 signaling to promote innate immunity, while exosomes isolated from systemic lupus erythematosus (SLE) patients' serum can produce abundant IFN-α, TNF-α, IL-1β, and IL-6 via the TLR1/2, TLR7, TLR9, and TLR4 pathways." (PMID 32565722, 2020).